RNU6-796P (RNA, U6 small nuclear 796, pseudogene)
Gene: Small nuclear RNA gene on chromosome 15 (84,939,617 to 84,939,723, reverse strand). Ensembl gene ENSG00000212388.
Homologues: Orthologues: chimpanzee U6 (99% identical), macaque U6 (89% identical). Paralogues in human: RNU6-86P (84% identical), RNU6-46P (82% identical), RNU6-11P (81% identical), RNU6-28P (81% identical), RNU6-37P (81% identical), RNU6-1 (79% identical), RNU6-1145P (79% identical), RNU6-1175P (79% identical), RNU6-1309P (79% identical), RNU6-2 (79% identical), RNU6-33P (79% identical), RNU6-345P (79% identical), and 1287 more.